CRHR2 (corticotropin releasing hormone receptor 2)
Diseases named in the same sentence as CRHR2 in open-access papers (continued):
Sharing a sentence is not in itself a finding about the gene and the disease.
pneumonia (1 paper, 2021). An acute, acute and chronic, or chronic inflammation focally or diffusely affecting the lung parenchyma, caused by an infection in one or both of the lungs (by bacteria, viruses, fungi, or mycoplasma.). "For instance, CRHR2 inhibition was shown to decrease neutrophil-mediated inflammation in a murine stress-pneumonia model." (PMID 34659221, 2021).
renal cell carcinoma (1 paper, 2024). "Interestingly, CRHR2 downregulation has also been demonstrated in renal cell carcinoma cases highlighting a disruption of an anti-angiogenic pathway." (PMID 37382757, 2024).
small intestinal disease (1 paper, 2021). "In our experiment, NSAID-induced small intestinal disease model rats intervened by berberine showed significantly change in HTR4, F2RL3, NPY, CRHR2, IL1b, VIP, AQP8, NOS1." (PMID 34284820, 2021).
tumor (16 papers, 2007 to 2024). "Crhr1 deletion suppresses the tumor development and growth in Apcmin/+ mice, while Crhr2 deficiency exacerbates the tumorigenicity." (PMID 33494263, 2021). "In conclusion, Crhr1 deficiency confers tumor-suppressing effects in Apcmin/+ mice, but Crhr2 deficiency worsens the tumorigenicity in both Apcmin/+ and AOM/DSS-treated mice." (PMID 33494263, 2021). "We found that the Crhr1 deficiency confers the tumor-suppressing effect in the Apcmin/+ mouse model, while the Crhr2 deficiency exacerbates the tumorigenicity in these two experimental models." (PMID 33494263, 2021). "Our ex vivo studies have showed that CRC compared to control tissues have reduced Fas expression, which is positively correlated with lost CRHR2 transcript levels, poor tumor differentiation and high risk for distant metastasis." (PMID 31614860, 2019). "In contrast, the Crhr2 deficiency promotes the tumor development and worsens the disease severity." (PMID 33494263, 2021). "Additionally, the expression of Fas ligand in CRC cells was correlated with a loss of CRHR2 mRNA, poor tumor differentiation and high risk for distant metastases (including LM)." (PMID 32429087, 2020). "Taken together, our findings suggest that blocking CRHR1-mediated responses inhibit tumor development and growth in an Apcmin/+ background, while inhibiting CRHR2-mediated responses promote tumorigenesis." (PMID 33494263, 2021). "In contrast, we found that both Apcmin/+; Crhr2−/− mice and Apcmin/+; Crhr2+/− mice had greatly increased numbers of tumors in their small intestine, compared to the tumor development in littermate Apcmin/+; Crhr2+/+ mice." (PMID 33494263, 2021). "Crhr1 deficiency not only inhibits the expression of tumor-promoting cyclooxygenase 2, but also upregulates tumor-suppressing phospholipase A2 in Apcmin/+ mice; however, Crhr2 deficiency does not change these expressions." (PMID 33494263, 2021). "Moreover it has been demonstrated that the CRH ligand Ucn promotes hepatic cancer cell migration by up-regulating cPLA2 expression via CRHR1 whereas it suppressed tumor cell migration by down-regulating iPLA2 expression via CRHR2." (PMID 27695045, 2016). "Additionally, it was found that YY1 is negatively regulated by corticotropin-releasing hormone receptor-2 (CRHR2)/Urocortin-2 (Ucn2) signaling, which can result in transcriptional de-repression of Fas and can resensitize the tumor to anti-Fas antibody-mediated apoptosis." (PMID 38539569, 2024). "Indeed, we observed that Crhr2 deficiency does not change the expression levels of Cox2 and Pla2 in the tumor tissues of Apcmin/+ mice." (PMID 33494263, 2021). "Through univariate Cox regression analysis, nine genes, including 3 oncogenes (HTR3C, CRHR2 and AGTR1), 6 tumor suppressor genes (CD8A, CD3E, SERPIND1, CXCR6, BMX and CD247) were proved to be correlated with the overall survival of EC patients." (PMID 38355782, 2024). "In turn, other studies show lower expression of CRHR2 in CRC tissues and cell lines compared to control, suggesting contrasting effects of CRHR2/Unc2 signaling on tumor growth and EMT, with decreased expression of EMT-inducers and elevated levels of EMT-suppressors." (PMID 32429087, 2020). "Lack of or significantly lower tumor expression versus control, which might also play a role in LM, was demonstrated for several NP/NP-Rs system components: CRHR2, GRP/GRPR, SM, Sst2, as well as Sst2 and Sst5." (PMID 32429087, 2020). "In our experimental model, ectopic induction of CRHR2 in CRC cell lines resulted in dramatic inhibition of the endogenous Ucn2 levels, while the receptor activation by exogenous Ucn2 reduced critically the tumor survival and expansion in vitro and in vivo in xenograft mouse models." (PMID 31614860, 2019).
cancer (10 papers, 2011 to 2025). A tumor composed of atypical neoplastic, often pleomorphic cells that invade other tissues. "CRHR2, INMT, and GALNT9 expression have been shown to be associated with cancer and may play a role in regulating the self-renewal and proliferation of cancer stem cells." (PMID 40358182, 2025). "Furthermore, the contribution of GNRH2, PRLH, GPR156, GRIK5, LHB, and CRHR2 to the neuroactive ligand-receptor interaction pathway are specified in ATLL in consistent with some other cancers." (PMID 34446027, 2021).
metabolic disorders (3 papers, 2012 to 2024). "Considering the pleiotropic role of CRHR2 gene in both mental and metabolic disorders, we hypothesized that risk variants in CRHR2 gene can predispose to MDD-T2D co-morbidity." (PMID 36077219, 2022).
inflammation (1 paper, 2019). Aberrant reaction of the microcirculation characterized by movement of fluid and leukocytes from the blood into extravascular tissues. "Another reason is probably because the anti-inflammatory effect of CRH depends on CRHR2 which induces a proinflammatory effect during acute colitis but confers protective activity during chronic inflammation." (PMID 30881446, 2019).
skin disorder (1 paper, 2026). Any deviation from the normal structure or function of the skin or subcutaneous tissue that is manifested by a characteristic set of symptoms and signs. "To better understand the link between stress and skin disorders, we aimed to investigate the differential expression of CRHR1 and CRHR2 in keratinocytes, depending on their level of differentiation." (PMID 41751472, 2026).
CRHR2 also shares sentences with these, for which no sentence is quoted: Anorexia (3 papers); breast carcinoma (3); Crohn disease (3); infection (3); mood disorder (3); autism (2); endometrial cancer (2); Hyperglycemia (2); irritable bowel syndrome (2); migraine (2); alcohol use disorder (1); alopecia (1); amyotrophic lateral sclerosis (1); anxiety-like behavior (1); Arthritis (1); asthma (1); atherosclerosis (1); Atrophy (1); autoimmune disease (1); cardiovascular diseases (1); chronic kidney disease (1); congestive heart failure (1); Crohn's colitis (1); emphysema (1); Endometrium (1); enteritis (1); epilepsy (1); generalized anxiety disorder (1); heart disease (1); heart failure (1).
A further 23 diseases each share a sentence with CRHR2 in 1 paper.